IDH2 (isocitrate dehydrogenase (NADP(+)) 2)
Diseases named in the same sentence as IDH2 in open-access papers (continued):
Sharing a sentence is not in itself a finding about the gene and the disease.
glioma (continued). "The IDH2 mutation was detected overall in 2.5% (23/923) of gliomas." (PMID 35996504, 2021). "The survival association in proneural glioblastoma was independent of the absence or presence of mutations in the genes encoding isocitrate dehydrogenase (IDH)-1 or IDH-2, a molecular marker that defines a clinically and molecularly distinct glioma entity with proneural gene expression." (PMID 33575479, 2021). "The IDH1 and IDH2 gene mutations can be used in clinical practice as strong prognostic biomarkers in gliomas as they could predict better survival." (PMID 35996504, 2021). "Indeed, most (>70%) diffuse grade II gliomas carry a recurrent missense mutation in the IDH1 or IDH2 (isocitrate dehydrogenase 1/2) genes, with IDH1R132H being the most commonly identified mutation (90%)." (PMID 33925547, 2021). "The IDH1-R132H mutation is by far the most common IDH1 or IDH2 mutation observed in glioma." (PMID 33806933, 2021). "It has been reported that an IDH1 mutation was potentially able to form glioma hypermethylation phenotype while IDH2 could promote acute myeloid leukemia." (PMID 35996504, 2021). "Mutations in IDH2 have been found in fewer than 3% of glial tumors." (PMID 34178638, 2021). "Mutations in the IDH1 and IDH2 genes usually occur in low-grade gliomas as well as secondary GBMs." (PMID 33237934, 2020). "Association of IDH1 and IDH2 gene mutations with clinical variables in glioma patients." (PMID 33552543, 2020). "Interestingly, MRS investigations have also identified lactate resonances in both IDH1 and IDH2 brain malignancies, and described IDH2 gliomas as more glycolytic than those harboring the IDH1 mutation." (PMID 32575619, 2020). "In fact, IDH1 and IDH2 mutations correlate with a better overall survival of glioma patients." (PMID 32316617, 2020). "In our study, only 2.4% (3/124) of the gliomas had IDH2 mutations." (PMID 32146731, 2020). "Mutations in IDH1 and IDH2 are observed in less than 5% of pediatric high-grade gliomas." (PMID 32977537, 2020). "And it is found that IDH1 mutations and IDH2 mutations are mutually exclusive in gliomas." (PMID 32280672, 2020). "These alterations, resulting from IDH1 and IDH2 mutations, could contribute to gliomagenesis through modifying epigenetic control and potentially the fates of stem or glioma progenitor cells." (PMID 32993063, 2020). "The gliomas described in these conditions are similar to the ones caused by sporadic variants in IDH1 or IDH2 for their frequent location in the frontal lobe and their prevalent histological type: more commonly diffuse low-grade or anaplastic gliomas than glioblastomas." (PMID 33282797, 2020). "IDH1/2 mutations should arise during embryonic development due to the somatic mosaic of mutant IDH1/2-expressing cells, such as IDH1 R132H/C/L/S or R100Q and IDH2 R140Q/G/W/L or R172K/G/M/Q/T/S, which are common mutations in gliomas (bold are the most frequent)." (PMID 31847543, 2020). "The isocitrate dehydrogenase gene 1 and 2 (IDH1/IDH2) mutational status and the hypermethylator phenotype [glioma CpG island methylator phenotype (G‐CIMP)], both characteristic of secondary GBMs and associated with longer survival times, were then considered to improve the TCGA classification." (PMID 31701625, 2020). "Frequency and nature of IDH1 and IDH2 mutations in glioma patients." (PMID 33552543, 2020). "Tumors with IDH1 or IDH2 mutations have distinctive genetic and clinical features, and patients with such tumors have a longer overall survival time compared to patients with wild-type gliomas." (PMID 32013066, 2020). "Interestingly, as early as 2014, a clinical study of oral AG-221 was carried out in patients with advanced solid tumors, including gliomas with IDH2 mutation and angioimmunoblastic T-cell lymphoma." (PMID 31263678, 2019).
glioma (continued). "The discovery of mutations in isocitrate dehydrogenase 1 (IDH1) and 2 (IDH2) in over 80% of low-grade gliomas (LGGs) and secondary glioblastomas has revolutionized pharmaceutical approaches to targeted therapies and the overall glioma classification schema." (PMID 31165048, 2019). "Other loci were found altered such as Aldehyde dehydrogenase 2 (ALDH2) and isocitrate dehydrogenase 2 (IDH2), that was found to predispose to cervical carcinoma and glioma respectively as well as BCL3, AKT2 and ERCC2 for which polymorphisms were shown to be associated with lung carninoma." (PMID 31105870, 2019). "This could be of importance, since the somatic mutations found in the IDH1/IDH2 gene are mostly found in low grade gliomas (LGG) and the proneural GBM subtype." (PMID 31574953, 2019). "In detail, they found that somatic mutations in IDH1 at R132 or IDH2 at R172 led to increased risk of glioma, hemangiomas and chondrosarcoma, and they demonstrated that the mutated IDH contributed to the increased cell proliferation, colony formation, and inability to differentiate." (PMID 30984620, 2019). "Second, because the symptoms of brain tumors typically include problems with speech, balance and hearing, hearing impairments associated with specific types of gliomas may be caused by IDH2 mutations." (PMID 29567975, 2018). "IDH1 or IDH2 mutations represent early genetic event in the complex process of glioma development." (PMID 30279357, 2018). "Somatic mutations of IDH1 and IDH2 have been reported to be associated with glioma CIMP." (PMID 29848370, 2018). "Thus, diffuse gliomas (WHO grades II–IV) are now molecularly stratified based on IDH1 or IDH2 mutational status, with gliomas of WHO grade II and III being stratified according to 1p/19q codeletion status." (PMID 30279357, 2018). "Mutations in IDH1/IDH2 are commonly considered to be glioma initiating." (PMID 29616301, 2018). "Mutations in IDH2 are seen more frequently in the 1p/19q-codeleted cluster, and appear to have regional grouping as well, indicating a unique type of DNA structure for these types of gliomas." (PMID 28532485, 2017). "Risk backpropagation analysis of our model identified IDH1 and IDH2 mutations (ranks 9, 10) as strongly associated with better prognosis, consistent with the role of these mutations as the primary feature in classifying gliomas." (PMID 28916782, 2017). "Mutation in IDH2 has been frequently found in cancers like gliomas and acute myeloid leukemia." (PMID 28900470, 2017). "Also, additional mutations in the IDH2 gene, apart from IDH2 R172 (e.g. R140), which in gliomas occur less frequently than those in the IDH1 gene, give the same phenotype." (PMID 28122345, 2017). "Given that the cytosolic pathway has been shown to be important in hypoxic reductive carboxylation for lipogenesis, and that gliomas appear to ‘favor’ IDH1 mutations, there may be a requirement for IDH2 wild‐type activity in hypoxic IDH1 mutant gliomas." (PMID 27196610, 2016). "IDH2 mutations are also significantly less common in glioma than their IDH1 counterparts suggesting that IDH1 mutations may be more advantageous to the tumor cells than IDH2 mutations." (PMID 28480226, 2016). "Our study revealed an intrinsic distinction between IDH1 and IDH2 mutant gliomas, and these mutations should be considered separately because their differences could have implications for the diagnosis and treatment of IDH1/2 mutant gliomas." (PMID 27245697, 2016). "Similar reduction of glutathione levels was also observed in glioma bearing IDH1 or IDH2 mutation which accumulates 2-HG, suggesting that this oncometabolite may support ROS formation through attenuating the anti-oxidant system." (PMID 27358718, 2016). "Initially, 5hmC loss in gliomas was proposed to be related with IDH1/IDH2 mutations." (PMID 26864347, 2016).
glioma (continued). "Moreover, mutations of IDH1 and IDH2 are mutually exclusive in gliomas, and biochemical investigations showed that IDH1 and IDH2 mutations differ in D-2-hydroxyglutarate (D-2HG) production in gliomas." (PMID 27245697, 2016). "Consequently, does energy production in IDH2-mutated gliomas favor oxidative phosphorylation over aerobic glycolysis?" (PMID 27245697, 2016). "Strikingly, mutations in IDH1 and IDH2 are mutually exclusive in gliomas." (PMID 27245697, 2016). "Although the genetic and epigenetic landscapes of IDH1 mutation gliomas have been extensively studied, whether IDH2 mutation gliomas have unique genetic and epigenetic characteristics that can be used as targets for future intervention is unknown." (PMID 27245697, 2016). "Among a total of 811 gliomas, IDH2 mutations were identified in 18 cases (2.2 %)." (PMID 27245697, 2016). "Mutations in IDH genes (IDH1 and IDH2) are observed in over 70% of low-grade gliomas and some GBM." (PMID 26485760, 2015). "IDH1 or IDH2 mutations (‘IDH mutations’) were present in 100 of 303 (33%) glioma tumors." (PMID 25797251, 2015). "A high level of 2-HG has been associated with missense mutations in IDH1 or IDH2 in glioma and several other tumor types and may be an effector of tumor cell dedifferentiation." (PMID 25091696, 2014). "In addition to IDH1 mutations, mutations in the homologous gene, IDH2, have also been identified in gliomas, but are much less common than the IDH1 mutations." (PMID 24932255, 2014). "The role of IDH2 mutations alone is still unclear because of the rare occurrence in gliomas: 1-2%." (PMID 24868540, 2014). "Mutation in the IDH1 or IDH2 genes occurs frequently in gliomas and other human malignancies." (PMID 24077826, 2013). "Whole exome sequencing of GBMs revealed frequent mutations at the position 132 arginine residue in the catalytic domain of Isocitrate Dehydrogenase 1 (IDH1) of progressive gliomas and targeted sequencing found additional mutations in the mitochondrial family member IDH2." (PMID 24077805, 2013). "The IDH2 mutations have also been described in gliomas, although at a lower frequency." (PMID 23894344, 2013). "Similarly, in vivo models are difficult to propagate and as a result, preclinical glioma models carrying the IDH1 or IDH2 mutation are scarce." (PMID 24252742, 2013). "Furthermore, MsMab-1 reacted with 10 IDH2 mutations including R172S and R172G, both of which have been reported in gliomas or chondrosarcomas." (PMID 24403254, 2013). "The predictive value of IDH1 and IDH2 mutations in gliomas remains controversial." (PMID 23894344, 2013). "In 2008, IDH1 and IDH2 mutations were first reported in low grade of gliomas and secondary GBM." (PMID 24217114, 2013). "Mutations in IDH1 and IDH2, frequently found in gliomas and acute myeloid leukemias (AML), are characterized by enzymatic gain of function and subsequent production of hydroxyglutarate, which inhibits several histone demethylases, including H3K9, H3K27, H3K36 and H3K4." (PMID 23356856, 2013). "We therefore reasoned that gliomas bearing IDH2 R172 mutations would also have elevated 2HG." (PMID 21326614, 2011). "Gliomas frequently contain mutations in the cytoplasmic NADP+-dependent isocitrate dehydrogenase (IDH1) or the mitochondrial NADP+-dependent isocitrate dehydrogenase (IDH2)." (PMID 21326614, 2011). "Mutations in IDH2 at codon 172 are present in grade II–III gliomas at a low frequency." (PMID 21625441, 2011). "Increased use of therapeutic strategies targeting mIDH1 may therefore also increase the proportion of glioma patients harboring IDH2 mutations, underscoring the need for the development of brain-penetrating PET tracers that can reliably detect mutations in both isoforms." (PMID 37049661, 2023). "Notably, all of the 1p/19q codel and GCIMP-high gliomas are mutated in IDH1 or IDH2." (PMID 37372972, 2023). "Besides, IDH1 and IDH2 mutations are early events in the development of gliomas." (PMID 34961815, 2021).
glioma (continued). "Consequently, mutant IDH1and IDH2 activity cause aberrant DNA and histone methylation, which lead to widespread hypermethylation of cytosine–phosphate–guanine (CpG) islands a phenomenon termed the glioma CpG-island methylator phenotype (G-CIMP)." (PMID 34277624, 2021). "Interestingly, the incidence of IDH1 and IDH2 mutations is elevated in gliomas." (PMID 32444979, 2020). "These cancer-associated IDH2 mutants gain neomorphic activity that converts α-KG to a reduced product (D)-2-hydroxyglutarate (D-2-HG), as high concentrations of D-2-HG can be detected in glioma and acute myeloid leukemia (AML) patients harboring these mutations." (PMID 32245484, 2020). "In addition, IDH1 has the mutation of homologous gene, IDH2 mutation was also found in glioma." (PMID 32582544, 2020). "Mutations of IDH2 are frequently observed in acute myeloid leukaemia, colon cancer, and gliomas, causing alterations in metabolism and DNA methylation; these mutations could represent a possible mechanism of tumorigenesis and provide potential avenues for therapeutic intervention." (PMID 31516386, 2019). "In addition to the further increase in the ratio of 2-HG/tCho, we found a significantly higher metabolite ratio of myo-Inositol/tCho in IDH2 gliomas (four patients with IDH2 R172K and one patient with IDH2 R172W mutations) compared to IDH1 gliomas (fifteen patients with IDH1 R132H mutation)." (PMID 30791611, 2019). "In addition, glioma subtypes can be identified by the IDH1/IDH2 mutation." (PMID 28851427, 2017). "The present study detected isocitrate dehydrogenase (IDH) 1 and IDH2 mutations in glioma to analyze whether IDH-mutated gliomas are situated in certain preferential areas and to investigate their correlation with magnetic resonance imaging (MRI) characteristics." (PMID 24932255, 2014). "Similar effects are seen due to elevated levels of the oncometabolite D-2-hydroxyglutarate in gliomas with activating variants of the IDH1 and IDH2 genes encoding the isocitrate dehydrogenase enzymes." (PMID 41546701, 2026). "These genes can have mutations which affect glioma growth and grading, with IDH1 mutations being more commonplace than IDH2 mutations." (PMID 41436375, 2026). "Voranigo (vorasidenib) is the first FDA-approved IDH1 and IDH2 inhibitor for the treatment of grade 2 IDH-mutant glioma." (PMID 40863132, 2025). "The ATRX, OLIG2, MGMT, and IDH2 networks highlight key molecular interactions that contribute to glioma development, progression, and therapeutic resistance." (PMID 40282990, 2025). "In glioma, the discovery of recurrent hotspot mutations in IDH1 and IDH2 genes has provided added rationale to investigate the association between altered metabolism and oncogenesis." (PMID 37398280, 2025). "Mutations in IDH1 (primarily) and IDH2 have been detected in up to 70% of WHO grade II and III gliomas, and are common in secondary GBMs that can arise from these lower grade malignancies." (PMID 41450919, 2025). "IDH gene mutations are present in approximately 50%–80% of WHO grade 2 and 3 gliomas, with IDH1 mutations being more prevalent than IDH2 mutations." (PMID 40809035, 2025). "IDH1 and IDH2 mutations frequently exist in multiple human malignancies, including acute myeloid leukemia (AML), glioma, glioblastoma, chondrosarcoma, and cholangiocarcinoma." (PMID 40863132, 2025). "One study investigated the presence of 20 common glioma mutations, including IDH1, IDH2, and ATRX, within the analyzed pituitary tumours, of which 1/248 tumours exhibited a loss of ATRX due to a large deletion within the gene." (PMID 40440300, 2025). "The hypericin-conjugated gold nanoparticles accumulate in glioma mitochondria and, upon red-light activation, induce oxidative stress and mitochondrial dysfunction, leading to a reduction in mutant IDH2 levels." (PMID 41008904, 2025). "Mutation in one of the two isocitrate dehydrogenases (IDH1 and IDH2) is very common in gliomas (70–80%)." (PMID 40983311, 2025).
glioma (continued). "Of all glial tumors, 24% (n = 20) and 22.9% (n = 19) carried the IDH1 or IDH2 mutation, respectively." (PMID 39316314, 2025). "An important molecular diagnosis marker is the genetic mutation in either isocitrate dehydrogenase 1 (IDH1) or isocitrate dehydrogenase 2 (IDH2), which is common in grade 2 and 3 gliomas and defining astrocytoma and oligodendroglioma." (PMID 40564198, 2025). "The IDH1 and IDH2 are frequently observed in various cancers, including gliomas and acute myeloid leukemia (AML)." (PMID 40183077, 2025). "IDH-mutant gliomas tend to have a missense mutation at codon 132 of IDH1, most commonly R132H, or at codons R140 or R172 of IDH2, such as R140Q or R172K." (PMID 41450919, 2025). "D-2HG accumulates in certain brain tumors, such as gliomas and glioblastomas, with gain-of-function mutations in the IDH1 and IDH2 genes encoding the IDH1 and IDH2 enzymes, respectively." (PMID 39201738, 2024). "On the other hand, IDH-mutant gliomas are characterized by a class-defining and possibly tumor-initiating clonal IDH1 or IDH2 gene mutation." (PMID 38539436, 2024). "It is important to keep in mind that the previous classification of central nervous system (CNS) tumors by the WHO in 2016 defined IDH1/IDH2 high-grade gliomas as GBM." (PMID 38891962, 2024). "Overall, approximately 80% of adult grade II/III gliomas and secondary glioblastoma multiforme (GBM) harbor mutations at either Arg132 of IDH1 or Arg172 of IDH2, whereas point mutations in the TERT promoter occurred in ~75% of GBM." (PMID 38232086, 2024). "Many gliomas, especially oligodendrogliomas, have mutations in isocitrate dehydrogenase 1 (IDH1) or isocitrate dehydrogenase 2 (IDH2), as well as deletions of chromosome arms 1p and 19q." (PMID 39594997, 2024). "Mutations in the metabolic enzymes isocitrate dehydrogenase 1 and 2 (IDH1 and IDH2) occur in more than 70% of low-grade glioma and approximately 12% of high-grade glioma." (PMID 37982850, 2024). "Reproducibility studies were performed using two FFPE glioma samples, cases 8 and 22, with IDH1 p.R132H and IDH2 p.R172K mutations respectively, by testing FFPE sections on three separate days." (PMID 38796421, 2024). "Mutations in the genes encoding IDH1 and IDH2 and, less commonly, IDH3 have been found in a variety of cancers, most commonly glioma, acute myeloid leukemia (AML), chondrosarcoma, and intrahepatic cholangiocarcinoma." (PMID 39000443, 2024). "Oligodendrogliomas are infiltrating gliomas that, by definition, possess mutations in the IDH1 or IDH2 genes and whole arm co-deletion of chromosomes 1p and 19q." (PMID 39707480, 2024). "We discovered that rat tumors lack the Idh1 R132 and Idh2 R172 hotspot mutations that are widely implicated in human gliomas (mainly in WHO grade II and III gliomas and secondary glioblastoma)." (PMID 38232086, 2024). "While mutation of both IDH1 and IDH2 isoforms are observed in a range of cancers, IDH1 R132H represents the main mutation (90%) in sporadic IDH mutant gliomas and is associated with more favorable outcomes." (PMID 39335096, 2024). "Alternatively, IDH2 localizes within the mitochondrial matrix, with mutations often driving AML, or less commonly, glioma." (PMID 39596840, 2024). "More recently, the dual IDH1/IDH2 inhibitor vorasidenib has been approved for the treatment of IDH-mutant glioma following surgery." (PMID 39409901, 2024). "Inhibitors of mutant IDH1 have been characterized, such as the recently FDA-approved Vorasidenib, a first-in-class dual inhibitor of mutant IDH1 and IDH2 with proven efficacy in IDH-mutant gliomas." (PMID 39518074, 2024).